PDCD4 (programmed cell death 4)
Diseases named in the same sentence as PDCD4 in open-access papers (continued):
Sharing a sentence is not in itself a finding about the gene and the disease.
cancer (continued). "The results of this study suggested that DTL bound with and down-regulated PDCD4 by ubiquitin degradation and promoted the migration, invasion and proliferation abilities of cancer cells." (PMID 31409387, 2019). "Utilizing a cohort of oropharyngeal SCC clinical samples with adjacent normal tissues (n = 6), we confirmed that PDCD4 mRNA is downregulated in cancer tissue and that this regulation is orchestrated by miR-21-5p and miR-499a-5p." (PMID 31235478, 2019). "PDCD4 can also bind ribosomes directly, affect the posttranscriptional translation process, and lead to cell apoptosis in cancer." (PMID 31384173, 2019). "An alteration in PDCD4 expression is pivotal to the pathogenesis of cancer and inflammation diseases." (PMID 31620370, 2019). "Using The Cancer Genome Atlas (TCGA) database, we also observed an increase in miR-21-5p levels and a decrease in PDCD4 transcripts across several other cancers." (PMID 31235478, 2019). "Both these miRs regulate downstream targets relevant to cancer progression and metastasis and thus, the inhibition of miR-21 is likely to produce an upregulation of PDCD4, a protein involved in programmed cell death." (PMID 31417117, 2019). "PDCD4-protein levels are usually down-regulated in cancer cells, but substantial numbers of patients with high PDCD4-protein levels in tumors show poor survival." (PMID 31075975, 2019). "For example, HA binding to CD44 promotes Nanog association with DROSHA/p68 microprocessor complex resulting in the upregulation of miR-21 and downregulation of PDCD4 (a tumor suppressor protein) in cancer cells." (PMID 31293964, 2019). "Considering the importance roles of PDCD4 in cancer progression, the regulation of PDCD4 level in cancers deserves more investigation." (PMID 31409387, 2019). "PDCD4 mRNA levels are decreased in many cancer tissues and cell lines as compared with the corresponding normal tissues." (PMID 31075975, 2019). "MiR-21 over-expression has been reported in several cancers and, in some cases, this has been related to concurrent PDCD4 down-regulation." (PMID 29707109, 2018). "Increased PRMT5 levels have been found to correlate with poor prognosis in various cancer, and in a follow up study, the same group further validated the association of PRMT5 with PDCD4." (PMID 30613353, 2018). "Programmed cell death 4 (PDCD4) is a well-known tumor suppressor gene in several cancers, its post-transcriptional activity is directly controlled by miR-21, whose over-expression has been recently reported in MPM compared to normal mesothelium." (PMID 29707109, 2018). "Among the candidates, PDCD4, a potent tumor suppressor gene that is frequently downregulated in human cancers, was predicted to be a miR-23a/b target by all three of the algorithms and was selected for further experimental verification." (PMID 28981115, 2017). "PDCD4 inhibits transformation, translation, invasion and intravasation, and its expression is down-regulated in several cancers." (PMID 29100302, 2017). "Some studies have found that PDCD4 is localized in the nucleus in normal cells and in the cytoplasm in cancer cells whilst others have reported opposite findings." (PMID 28750063, 2017). "MicroRNA-21 (miR-21) is a key oncomiR significantly elevated in the majority of human cancers that exerts its oncogenic activity by targeting the tumor suppressor gene programmed cell death 4 (PDCD4)." (PMID 28881718, 2017). "Substantial data indicate that PDCD4 is consistently downregulated in human cancers and cancer cell lines." (PMID 28881718, 2017). "PDCD4 reportedly acted the tumor suppressor in repressing the transformation and immortality of cancer cells." (PMID 27983653, 2016). "The anti-apoptotic capabilities of MIR21 in cancer cells are manifested through the ability to suppress critical apoptotic genes including programmed cell death 4 (PDCD4, previously referred to as neoplastic transformation inhibitor)." (PMID 27084064, 2016).
cancer (continued). "SRSF3 silencing was noted to reduce the relative level of PDCD4 isoform 2, containing the partial PDCD4 intron 3 in distinct cancer cells." (PMID 27983653, 2016). "In PDCD4-knockdown cancer cells, epithelial cadherin 1 (E-cadherin) promoter activity was inhibited." (PMID 27852288, 2016). "Both PTEN and PDCD4 were identified as the upstream suppressors of matrix metallopeptidase 9 (MMP-9) which facilitated cancer cell migration through degrading the collagenous substrates in the surrounding extracellular matrix." (PMID 27533461, 2016). "While PDCD4 has been extensively studied in cancer cells and tissues, there are very limited studies on PDCD4 functions in stromal cells, specifically one implicating it in negative regulation of αSMA through unspecified mechanisms." (PMID 27542230, 2016). "PDCD4 is also regulated at the mRNA level by microRNA (miR)-21, which is overexpressed in a variety of cancers." (PMID 26595526, 2016). "More recently, antisense studies targeting mature miR21 suggested that blocking miR21 function can induce apoptosis by activating expression of the programmed cell death 4 (PDCD4) protein in certain types of cancer cells, e.g. HeLa cells and MCF-7 cells." (PMID 26405811, 2015). "PTEN and PDCD4 are the common target genes regulated by miR-21 and both contribute to the anti-cancer effect of herbal products." (PMID 26305257, 2015). "The identified targets of miR-21 in human cancer cells include a tumor suppressor protein [Program Cell Death 4 (PDCD4)]." (PMID 24606718, 2014). "MiR-21 is upregulated in many types of malignant tumors and has been identified as an antiapoptotic miRNA which can directly target programmed cell death protein 4 (PDCD4) and phosphatase and tensin homolog (PTEN)." (PMID 25126546, 2014). "PDCD4 can inhibit the transformation, migration, and invasion of cancer cells in vitro, and overexpression of PDCD4 in transgenic mice was found to significantly suppress tumorigenesis." (PMID 25196934, 2014). "Among them, miR-21 is overexpressed in many kinds of cancer and is a negative regulator of expression of the tumor suppressor gene programmed cell death 4 (PDCD4)." (PMID 24516357, 2014). "It has been reported that miR-21 was upregulated in most malignant cancers, the proposed mechanism of which was through suppressing expression of programmed cell death 4 (PDCD4)." (PMID 25400316, 2014). "Although these studies demonstrated mechanisms of invasion regulated by PDCD4, the mechanisms that regulate PDCD4 in cancer cells are not well understood." (PMID 20831814, 2010). "PDCD4 has been identified as a suppressor of tumorigenesis with lost or reduced expression in cancers of epithelial origin, including the lung, breast, colon, esophagus, and ovary." (PMID 20831814, 2010). "There was a significant difference in Pdcd4 cellular localization between normal and cancer tissues (p = 0.002)." (PMID 19728867, 2009). "In this study, we also demonstrated similar results with other groups that a differential expression pattern of Pdcd4 was found between normal and carcinoma cells by IHC analysis." (PMID 19728867, 2009). "Positive Pdcd4 staining at the ovarian surface epithelium was observed in 11 out of 13 (84.6%) normal samples and 18 out of 44 (40.9%) carcinomas." (PMID 19728867, 2009). "The expression of Pdcd4 was also assessed by immunohistochemical analysis in 13 ovarian normal tissues and 44 carcinomas." (PMID 19728867, 2009). "The expressions of Pdcd4 in both ovarian borderline tissues and carcinomas were significantly lower than the expression in normal ovarian tissues (p < 0.001)." (PMID 19728867, 2009). "New research suggests that PDCD4, in addition to its known functions in cancer, regulates oxidative stress, inflammation, and metabolic pathways, which might put it at the root of a number of metabolic illnesses." (PMID 40766329, 2025). "In addition to its cardiovascular functions, PDCD4 plays a critical role in tumorigenesis and cancer progression." (PMID 40766329, 2025).
cancer (continued). "According to our findings, several forms of cancer have unique patterns of PDCD4 expression." (PMID 40766329, 2025). "PDCD4 has emerged as a critical tumor suppressor gene with multifaceted roles in cancer biology." (PMID 41614853, 2025). "Therefore, reduced PDCD4 expression correlates with increased invasion, metastasis, and a poor prognosis in cancer patients." (PMID 40004462, 2025). "The fact that PDCD4 influences genomic stability, patient prognosis, and immune modulation implies that it could serve as a link between the biology of cancer and the progression of AF." (PMID 40766329, 2025). "PDCD4, a pro-inflammatory tumor suppressor protein, is consistently reduced in human cancers." (PMID 38726321, 2024). "Future antiapoptotic cancer therapeutics may focus on the PDCD4 protein due to its ability to suppress neoplastic transformation." (PMID 38503934, 2024). "Furthermore, the PDCD4 is highly conserved among vertebrates and is frequently downregulated in multiple different types of cancer, including colon, liver, breast, lung, pancreas, and more." (PMID 36826085, 2023). "Based on another study, it was concluded that miRNA-183 played a crucial role in the advancement of cancer cells by promoting oesophageal squamous cell carcinoma cell proliferation and invasion via binding to the PDCD4 mRNA and this was in parallel with our results." (PMID 37808196, 2023). "Metascape database analysis revealed that the target mRNAs PRKACB and PDCD4 of miR-550a-3p as well as RPS6KA5 and BCL2L2 of miR-550a-5p were associated with miRNA cancer pathway, providing important clues for subsequent studies on the mechanism underlying EAC development." (PMID 36829221, 2023). "They explored miR-499 for its involvement in PDCD4 regulation in various cancers." (PMID 35955412, 2022). "Both PDCD4 mRNA and protein are now more frequently measured in cancers of the GI tract and compared to miRNA expression, as exemplified by the investigations subsequently outlined in this review, often with an inverse correlation showing a possible molecular relationship between them." (PMID 35847932, 2022). "Although not all cancers exhibit decreased PDCD4 expression, which diminishes the potential use of PDCD4 expression as a diagnostic tool, decreased expression is very frequently associated with poor prognosis." (PMID 35847932, 2022). "Enriched pathways for upregulated miRNAs included: “Chemical carcinogenesis–receptor activation” (p-value = 0.018) associated with ESR1, FGF18, JAG1, KPNA6, PPARA genes; the pathway “Proteoglycans in cancer” (p-value = 0.089) associated with genes ESR1, FRS2, HIF1A, PDCD4." (PMID 36359024, 2022). "MicroRNA and PDCD4 expression in cancers of the gastrointestinal tract." (PMID 35847932, 2022). "PDCD4 has been well characterized as a translational repressor in the cytoplasm of cancer cells." (PMID 34617965, 2021). "PDCD4 is a significant functional target of miR-21-5p in various types of cancers." (PMID 34249905, 2021). "The role of PDCD4 in cancer progression is still being defined." (PMID 33801444, 2021). "Interestingly, macrophages reduce PDCD4 expression in cancer cells by mTOR-mediated proteasomal degradation." (PMID 34917890, 2021). "High miR-21 and low ITGβ4 and PDCD4 expression mark the metastasis of cancer." (PMID 34439865, 2021). "The precise elucidation of the upstream regulatory network that controls PDCD4 in cancer and immune cells may be important to define novel anti-cancer and anti-inflammatory strategies." (PMID 34917890, 2021). "MiR-21 suppression was followed by PDCD4 overexpression with anti-cancer effects." (PMID 34295245, 2021). "Indeed, PDCD4 levels have been shown to be regulated by miR-21 in cancer models increasing transformation, invasion, and metastasis." (PMID 32747606, 2020). "The up‐regulation in PDCD4 expression is seen during apoptosis, indicating that the reduction in PDCD4 expression may render cancer cells anti‐apoptotic." (PMID 33089961, 2020).
cancer (continued). "The expression of the tumor suppressor PDCD4 is downregulated in many types of cancer." (PMID 31952347, 2020). "The expression of PDCD4 undergoes down-regulation in a number of cancers." (PMID 32612456, 2020). "The tumor suppressor programmed cell death 4 (PDCD4) protein was first described in cancer studies and has been shown to regulate protein synthesis by inhibition of EIF4A helicase activity and via interaction with specific RNA motives present in a particular subset of target mRNAs." (PMID 32747606, 2020). "The results suggested serum exosomal miRNA 21 may regulate cell progression by suppression of PDCD4 via proteoglycans in cancer pathway in CRC." (PMID 32925795, 2020). "Moreover, PDCD4 is an important factor in angiogenesis besides its role in inflammation and cancer prevention." (PMID 33304903, 2020). "Moreover, cancer patients with higher DTL expression owned lower survival rate, and functional experiments found that DTL enhanced the motility and proliferation of cancer cells through degrading PDCD4 to promote the development of cancers." (PMID 32596316, 2020). "Therefore, we reviewed the recently emerging pleiotropic regulation of PDCD4 by ncRNAs in cancer and inflammatory disorders and aimed to shed light on the mechanisms of associated diseases, which could be conducive to the development of novel treatment strategies for PDCD4-induced diseases." (PMID 31620370, 2019). "Thus, therapeutic strategies based on PDCD4 manipulation are promising treatments for cancer or inflammatory disorders." (PMID 31620370, 2019). "Our results suggested DTL promote cancer progression through degrading PDCD4." (PMID 31409387, 2019). "Therefore, miR-21/PDCD4 signaling pathway was considered as potential targets for novel cancer prevention or anti-inflammatory therapies." (PMID 31035975, 2019). "Since both miR-21 and miR-499 have been shown to regulate the expression of PDCD4 in a diverse range of cancers, we asked whether these miRNAs interact in their regulation of PDCD4." (PMID 31235478, 2019). "The summary of ncRNA that regulate PDCD4 in different cancers and inflammatory disorders." (PMID 31620370, 2019). "However, in a disease setting such as cancer, PDCD4 is frequently downregulated, and its expression has been correlated with disease progression in various malignancies." (PMID 31235478, 2019). "Since certain elevated levels of miRNAs and lncRNAs may also contribute to cancer promotion, more consideration should be taken in targeting of the ncRNA/PDCD4 pathway during the treatment of inflammatory diseases." (PMID 31620370, 2019). "PTEN and PDCD4 have been previously shown to impede cancer cell growth and facilitate apoptosis, while RECK could reduce cancer cell mobility by deactivating matrix metalloproteinases." (PMID 30736829, 2019). "Recently, published studies have demonstrated that the miRNA/PDCD4 axis could modulate chemosensitivity in resistant cancers." (PMID 31620370, 2019). "In addition to affecting the resistance of cancer cells, there are also some drugs that can directly regulate the level of miRNA/PDCD4, thus serving as a potential therapeutic application." (PMID 31620370, 2019). "Interestingly, miRNAs targeting PDCD4, including miR-21 and miR-23, have been tested in clinical trials via liposomes or other strategies for the treatment of inflammatory diseases and cancer." (PMID 31620370, 2019). "Therefore, the current study aimed to investigate the expression levels of miR-196a2, three of its putative targets; ANXA1, DFFA and PDCD4 mRNAs and annexin A1 protein in GI cancer tissue samples compared to cancer-free tissues." (PMID 29091952, 2017). "Therefore, miR-21 and PDCD4 were considered as potential targets for novel cancer prevention or anti-cancer therapies." (PMID 28881718, 2017).
cancer (continued). "KHSRP knockdown also inhibited the maturation of cancer-associated miRNAs, such as miR-21, miR-130b, and miR-301, and induced the expression of their target mRNAs, such as BMP6, PDCD4, and TIMP3, resulting in the inhibition of epithelial-to-mesenchymal transition." (PMID 29254151, 2017). "Regulation of PDCD4 by miR-208a-3p may explain why the upregulation of miR-208a-3p during carcinogenesis can promote cancer progression." (PMID 27634902, 2016). "The potential ability of MIR21 to interact with PDCD4 leading to posttranscriptional gene regulation of PDCD4 protein expression in the maturing pig oocyte as demonstrated herein has also been described in several types of cancer cells." (PMID 27084064, 2016). "Preclinical studies have indicated that PDCD4 could control key genes involved in cancer migration and metastasis." (PMID 27852288, 2016). "Accumulation of cytoplasmic PDCD4 protein is reported in both normal and cancer cell lines." (PMID 27852288, 2016). "We observed that PDCD4 protein levels were significantly lower in the cancer tissues." (PMID 27021515, 2016). "Among the validated miR-21 target genes, PDCD4 plays an important role in cancer cell migration." (PMID 25582055, 2015). "Furthermore, the inhibition of miR-21 can regulate the expression of phosphatase tensin homologue (PTEN) and programmed cell death 4 (PDCD4) in cancer cells." (PMID 24959246, 2014). "Given that all the patients studied carried malignant tumours with an assigned Dukes' stage, the data suggest that during progression of malignancy increasing amounts of miR-21 lead to inhibition of translation of the already decreased levels of PDCD4 mRNA." (PMID 25310697, 2014). "Since PDCD4 and HSP27 have previously been associated with cancer and regulation of cell growth and apoptosis, these proteins may have novel implications in CLL cell survival and represent potential therapeutic targets." (PMID 20661426, 2010). "Since miR-21 is over-expressed and it has been shown to regulate PDCD4 in other cancers, we sought to determine whether miR-21 regulates PDCD4 in OSCC." (PMID 20831814, 2010). "Despite all of these studies showing PDCD4 deregulation associated with important clinical parameters in different cancers, the regulatory mechanisms of PDCD4 are still not completely understood." (PMID 20831814, 2010). "The expression levels of PDCD4 were reduced in many human progressed carcinomas." (PMID 19480673, 2009). "Erioflorin stabilizes the tumor suppressor protein Pdcd4 (Programmed Cell Death Protein 4), with the consequent transcriptional activity inhibition of Activator Protein-1 (AP-1) and NF-κB, which are crucial for cancer cell survival and proliferation in advanced stages of cancer." (PMID 40126263, 2025). "Moreover, recent studies indicated that the miRNA/PDCD4 axis could modulate chemosensitivity in multiple resistant cancers." (PMID 35795053, 2022). "This leads to the question of why is there simultaneous expression of several microRNAs that can individually downregulate PDCD4 in certain cancer cells and suggests it might be likely that the tumorigenic agent is upstream- and similarly effects expression of these miRNAs." (PMID 35847932, 2022). "PDCD4 expression in neurons is altered by injury and stress, and recent work has shown that, as in cancer cells, PDCD4 may act as a translational repressor in neurons." (PMID 34617965, 2021). "MiR-21 role in cancer has been extensively studied and its upregulation may explain the intrinsic resistance of some cancers to chemotherapy, being miR-21 and PDCD4 inversely correlated in CRC." (PMID 32410997, 2020). "While the mechanisms underlying PDCD4 downregulation in cancer cells have been reported, whether or not the PDCD4 protein levels are regulated by autophagy is unclear." (PMID 31952347, 2020). "The data indicate that PDCD4 may be a promising target for the cancer prevention and therapy." (PMID 31075975, 2019).